IL18 (interleukin 18)
Diseases named in the same sentence as IL18 in open-access papers (continued):
Sharing a sentence is not in itself a finding about the gene and the disease.
melanoma (continued). "Pathway enrichment revealed multiple and highly relevant signaling cascades enriched in dermal melanoma cells, such as senescence, PI3K‐AKT signaling, and IL‐18 signaling." (PMID 37602975, 2023). "The contribution of IL18+ cells and NLRP1+ cells was decreased in stromal areas in melanoma compared with control samples by IHC experiment (melanoma and control groups, n = 4, respectively)." (PMID 37620327, 2023). "We found that keratinocytes secrete IL18, IL1ra, MIF and Serpin E1, level of which was increased in keratinocytes incubated with melanoma-conditioned media, as compared to control cells." (PMID 36123693, 2022). "MDSC are potent suppressors of the anti-tumor immune response, with administration of IL-18 shown to increase the population of MDSC in multiple myeloma and in a murine model of melanoma." (PMID 31231372, 2019). "Ten melanoma patients and nine RCC patients were enrolled in a previous study and were assigned to different doses (100, 500, 1000 or 2000 μg/kg) of IL-18." (PMID 31492049, 2019). "Of note, a significant positive correlation between IL18 expression and survival rates was found in SKCM, which has lower IL18 expression than normal tissues, implying that the malignancy of melanoma is due to the lower IL18 expression." (PMID 31731729, 2019). "Exogenous IL-18 directly enhances the migration and invasion of a melanoma cell line, B16F10, suggesting that IL-18 has critical roles in melanoma malignancy." (PMID 31731729, 2019). "For instance, administration of recombinant IL-18 has been shown to activate CD4+ T cells and/or NK cell immune responses, suppressing the growth and metastasis of melanoma cells in vivo." (PMID 31231372, 2019). "NK cells, cultured with IL-2, IL-15 or IL-15/IL-18 and in the presence of either BRAF-i or MEK-i, were analyzed for their ability to kill different melanoma cell lines including MeCoP, MeTA, MeDeBO and FO-1." (PMID 27563819, 2016). "A combination of IL-18 and IL-21 has been used in clinical trials on NHL and melanoma; the regimens were well tolerated and provided significant clinical benefits." (PMID 25686210, 2015). "As shown with melanoma, mRNA levels of IFN-γ, TNF-α, IL-2, IL-18, IL-10, and VEGF-A were significantly decreased in kCYC mice compared with WT mice in draining LNs on day 14 (p < 0.05, respectively)." (PMID 26098776, 2015). "The presence of an inflammatory response in the B16 melanomas treated with LTX-315 was further indicated by increased mRNA levels of inflammatory cytokines such as interleukin (IL) 1β, IL6 and IL18 in the tumor tissue and of IL6 in plasma samples." (PMID 24676901, 2014). "Second, resveratrol inhibited IL-18-dependent expression of VCAM-1 by tumor-activated hepatic sinusoidal endothelium, preventing melanoma cell adhesion to the microvasculature." (PMID 21569399, 2011). "Due to the powerful antitumor potential of IL-18, it has been used in preclinical studies as a tool to increase the proliferation, survival and cytotoxicity of CAR T cells (Chimeric Antigen Receptor T cells) in melanoma and small cell lung cancer." (PMID 37298187, 2023). "Moreover, IL-18 levels were shown to be correlated with higher CD8+ T cells, NK cells infiltration and activity in colorectal cancer, melanoma and thyroid carcinoma." (PMID 37298187, 2023). "The initial findings from the enzyme-linked immunosorbent assay (ELISA) indicated a statistically significant downregulation of pyroptosis protein expression in melanoma patients when compared to the control group, especially NLRP1, GZMA, and GSDMB, followed by CHMP4A and IL18." (PMID 37620327, 2023). "In children with ASD, an increase in the NLRP3 inflammasome and another inflammasome complex, absent in melanoma 2, and accordingly the production of IL-1β and IL-18 inflammatory cytokines were observed." (PMID 38026692, 2023).
melanoma (continued). "Data reported in the present study support the hypothesis of a beneficial autoimmunity mediated by NOD2, IL-18 and ADRB2, since their expression is shown to be almost abolished in melanoma patients." (PMID 35205739, 2022). "On the other hand, patients with colorectal cancer and patients with melanoma who present early metastasis have higher values of IL-18 in their sera than patients without metastasis." (PMID 36678726, 2022). "In this work we show that systemic expression of IL-12 plus IL-18 induced an alteration in the normal TVM vs TMEM/TEFF distribution in secondary lymphoid organs and a preferential enrichment of TVM cells in the melanoma (B16) and the pancreatic ductal adenocarcinoma (KPC) tumor models." (PMID 36330506, 2022). "Expression levels of NOD2, BAX, IL-18 and ADRB2 were found to be significantly different in melanoma vs. controls and discriminate melanoma from controls in an extremely effective way, either as single molecules (AUC > 0.93 in all cases) or as a profile, according to the PCA analysis." (PMID 35205739, 2022). "Although there are conflicting reports about the roles of IL-18 in melanoma progression, the clinical relevance of IL-18 expression has not been comprehensively studied." (PMID 31731729, 2019). "Although there have been many conflicting reports about the roles of IL-18 in tumors, there has been no comprehensive analysis of the clinical relevance of IL-18 expression in melanoma." (PMID 31731729, 2019). "Similarly, a previous study revealed that in the blood of melanoma cell-infiltrated livers, TNF-α and IL-1β were inhibited, and IL-18 augmentation was prevented by treatment of resveratrol." (PMID 30670927, 2018). "In addition to mouse melanoma, we also confirmed that ERDR1 expression was increased by IL-18 siRNA transfection in a human gastric cancer cell line." (PMID 26901187, 2016). "This was further supported by in vitro experiments where RVL also inhibited IL-18 secretion, VCAM-1 expression and melanoma cell adhesion to tumor-activated HSE cells, three interrelated events regulating the microvascular arrest of circulating melanoma cells in the liver." (PMID 21569399, 2011). "The unexpected result of no measurable IL-18 in our culture spent medium suggests that melanoma from our patient population includes ultraviolet radiation-induced melanoma." (PMID 24281094, 2010). "Similarly, the adenoviral delivery of an IL18-coding gene to mouse melanoma B16-F10 cells (which per se do not express flIL18) limited their growth upon inoculation into WT C57BL/6 mice." (PMID 40263267, 2025). "The combinatory therapy of immunostimulatory cytokines IL-1β, IL-18, or IL-12 with GSDMD-based pyroptosis while not causing systemic adverse effects generates a robust antitumor response, ultimately leading to long-term remission in mouse melanoma model." (PMID 39737979, 2024). "Bacteria expressing murine decoy-resistant IL18 mutein (DR18) induced robust CD8+ T and NK cell-dependent immune responses leading to dramatic tumor control, extending survival, and curing a significant proportion of immune-competent mice with colorectal carcinoma and melanoma." (PMID 38562821, 2024). "Although the clinical evidence implied that melanoma skin tissue reduced GZMA, GSDMB, NLRP1, IL18, and CHMP4A expression in epidermal, however, the result obtained with bulk-sorted samples could not explain the main scientific questions on cell sources heterogeneity." (PMID 37620327, 2023). "However, according to our best knowledge, no one has described the enhanced production of IL18 in keratinocytes under the influence of melanoma." (PMID 36123693, 2022). "As such, the role of IL-18 in tumor progression remains controversial, and there is no comprehensive analysis of IL-18 expression and its correlation with clinical outcomes in patients with melanoma." (PMID 31731729, 2019). "Unlike IL-1β, IL-18 is pretty low in melanoma cells, even undetectable." (PMID 28360909, 2017).
melanoma (continued). "Erdr1, which is inversely correlated with IL-18, exhibits a negative role in melanoma progression." (PMID 26784177, 2016). "Our results also revealed that RVL blocked both in vitro VLA-4-dependent microvascular adhesion and proliferation in IL-18-treated melanoma cells, suggesting that RVL may also exert its antimetastatic effect by preventing melanoma cell response to endogenous hepatic IL-18." (PMID 21569399, 2011). "Rolling and early adhesion of B16M cells to the HSE, IL-1-dependent endothelial release of H2O2 through IL-18, and late adhesion of surviving melanoma cells are sequential steps during B16M cell attachment to the HSE that occur in a short period (3–6 h), and enhance melanoma cell adhesion." (PMID 24281071, 2010). "Cluster 3 had high expression of these genes, such as NOD2 and IL18, and high PScore, but according to survival analysis, this model based on metastatic melanoma patients may not be suitable for primary melanoma patients." (PMID 38229080, 2024). "For example, CASP4, NLRP1, MEFV, IL18, and NINJ1 correlated positively with GSDMD in metastatic melanoma patients but not in primary melanoma patients." (PMID 38229080, 2024). "Taken together, the negative correlation between Erdr1 and IL-18 suggests a potential anti-inflammatory effect that occurs through regulation of inflammatory response-related molecules such as HSP90 and STAT3, which are also candidates to be targeted for melanoma therapy." (PMID 27941650, 2016).
psoriasis (100 papers, 2007 to 2025). An autoimmune condition characterized by red, well-delineated plaques with silvery scales that are usually on the extensor surfaces and scalp. "Kato et al5 reported a single nucleotide polymorphism in the IL-18 gene linked to psoriasis, indicating a role in psoriasis susceptibility through altering IL-18 production." (PMID 39834723, 2025). "Both IFN-γ and TNF-α are known to induce the expression of IL-6, IL-8, IL-12, and IL-18, thereby constituting a key regulatory axis within the cytokine network implicated in psoriasis." (PMID 40731810, 2025). "Other cytokine therapies should be tested including anti-IL-17 and anti-IL-18 which are approved for use in other inflammatory conditions such as psoriasis and NLRC4/XIAP deficiencies respectively." (PMID 39132307, 2024). "NLPR1 inflammasome has been implied in prompting the onset of psoriasis, either by increasing the susceptibility to psoriasis or by dysregulated release of pro-inflammatory cytokines including IL-1β and IL-18." (PMID 38347543, 2024). "This literature review will address the most recent updates regarding IL-18 and IL-18BP in psoriasis, atopic dermatitis, rosacea, and bullous pemphigoid and discuss the underlying impacts of IL-18 and IL-18BP and inflammatory disease in the skin." (PMID 36742296, 2023). "IL-18 has been implicated to play a role in psoriasis, atopic dermatitis, rosacea, and bullous pemphigoid in human inflammatory skin diseases." (PMID 36742296, 2023). "Serum levels of IL-18 were provided in five studies and pooled SMD was 1.27 (95% CI: 0.64–1.90; P < 0.001), indicating elevated levels of IL-18 in peripheral blood were associated with psoriasis risk." (PMID 37883350, 2023). "They reported a higher transmission of the rs878329C and rs8079034C genotype in psoriasis patients and correlated the rs878329C allele with elevated circulating IL-18 levels." (PMID 37443800, 2023). "An important modulator in the HPA axis and AD pathogenesis is IL-18, a member of the IL-1 cytokine family implicated in various immune-mediated skin disease including AD, psoriasis, alopecia areata, dermatomyositis, and cutaneous lupus erythematous." (PMID 35572606, 2022). "Overall, the GCF levels of IL-18 and E-selectin were associated with moderate to severe psoriasis based on clinical and histopathological diagnoses." (PMID 34685372, 2021). "It was reported that increasing IL-18 secretion promotes the maintenance and development of Th17 cells, which are broadly associated with autoimmune inflammatory diseases, such as psoriasis." (PMID 34072753, 2021). "IL-18 has been implicated in various inflammatory skin diseases, including psoriasis, atopic dermatitis (AD), urticaria, contact dermatitis, alopecia areata (AA), drug allergy, graft-versus-host disease (GVHD), cutaneous lupus erythematosus (CLE), and etc.." (PMID 26690141, 2015). "IL18 also stimulates IFNγ production, and the presence of polymorphisms in the IL18 gene (rs187238) was associated with susceptibility to psoriasis in Japanese patients." (PMID 24069534, 2013). "IL-22, IL-20, IL-26 and IL-18 have all been implicated in inflammatory conditions such as Crohn's disease and Psoriasis in humans." (PMID 20950493, 2010). "In particular, it would be valuable to determine whether elevated baseline IL-18 activity might predict future secondary loss of response to biologic therapy in psoriasis." (PMID 40650209, 2025). "Despite advances in understanding their underlying mechanisms, recent research highlights the significance of interleukins IL-18 and IL-37, in Th1, Th2, and Th17 inflammatory responses, closely associated with the pathogenesis of psoriasis and atopic dermatitis." (PMID 39126010, 2024). "These pieces of evidence indicate that IL-18-mediated T cell response may hold an implicated role in psoriasis, and the inhibition of IL-18 can be a potential therapy for psoriasis." (PMID 36742296, 2023).
psoriasis (continued). "Furthermore, IL-18 and IL-18BP are also implicated in developing psoriasis, atopic dermatitis (AD), lupus erythematosus (LE), and other inflammatory skin diseases." (PMID 36742296, 2023). "The expression of many genes known to be associated with psoriasis, including Lce3f, Sprr2b, Krt15, S100a8, S100a9, Il17a, Il17f, Il18, Il20, Il22, and Ccl20, was downregulated in the skin of IMQ-treated Camk4−/− mice compared with those of IMQ-treated Camk4+/+ mice." (PMID 35869084, 2022). "The relevant findings further indicated that high levels of IFN-γ, IL-12 and IL-18 may be associated with psoriasis severity." (PMID 34290604, 2021). "Because serum IL-18 concentration is linked to psoriasis severity (PASI), IL-18 might be considered as a possible biomarker of psoriasis." (PMID 27941650, 2016). "Finally, the diagnostic precision of GCF IL-18 and sE-selectin for psoriasis was tested." (PMID 34685372, 2021). "IL-18 promotes angiogenesis and tumor suppression and has been found to be elevated in nearly all inflammatory diseases—from psoriasis and atopic eczema to pancreatitis and infections." (PMID 40731810, 2025). "Results showed that IFN-γ, TNF-α, IL-1β, IL-6, IL-17A, IL-18, and IL-23 in psoriasis patients had significantly higher levels compared to controls and a strong correlation between PASI scores and these cytokines." (PMID 40699767, 2025). "Recent studies have shown that IL-18 levels remain significantly elevated in psoriasis patients even after clinically effective therapy." (PMID 40650209, 2025). "CASP1 has long been recognized as a central mediator of IL-1β and IL-18 processing, two cytokines that contribute to the chronic inflammation in psoriasis." (PMID 40771724, 2025). "IL-18 has been documented in its relation to a variety of dermatologic diseases (eg, psoriasis, rosacea)." (PMID 39834723, 2025). "ELISA further confirmed that PSVII reduced the levels of IL-1β and IL-18 in the peripheral blood of psoriasis mice." (PMID 40405066, 2025). "The elevated levels of IL-6 and IL-18 also correlate with inflammatory responses, as observed in the control psoriasis group in the referenced meta-analysis." (PMID 40678000, 2025). "IL-18 promotes the activation and proliferation of T cells, particularly Th1 and Th17 cells, which are known to play central roles in the pathogeneses of psoriasis and T1DM." (PMID 40277935, 2025). "Pyroptosis is a highly inflammatory process that leads to the release of pro-inflammatory cytokines like IL-1β and IL-18, which are known to contribute to the chronic inflammation observed in psoriasis." (PMID 40771724, 2025). "They found that the levels of IL-18 were significantly elevated in patients with psoriasis compared to healthy subjects." (PMID 40731810, 2025). "Elevated serum IL-18 levels have been reported in patients with psoriasis compared to healthy individuals." (PMID 40650209, 2025). "Numerous studies have demonstrated that the serum levels of TNF-α, IFN-γ, IL-6, IL-8, IL-12, IL-18, and IL-30 are significantly elevated in patients with active psoriasis compared to healthy individuals." (PMID 40731810, 2025). "Although IL-18 has been shown to regulate both Th1 and Th17 cells in psoriasis and to stimulate both Th1 and Th2 responses in atopic dermatitis, such dual regulation has not been observed in other infectious diseases, to the best of our knowledge." (PMID 40489556, 2025). "Immunohistochemical analysis revealed IL-18 protein in the basal keratinocytes of normal skin, with a marked increase in expression in suprabasal keratinocytes in psoriasis patients." (PMID 40731810, 2025). "In psoriasis, a chronic inflammatory skin disease, IL-1β and IL-18 are increased, and excessive NLRP3 and caspase-1 expression levels are associated with its development." (PMID 39684233, 2024). "These heightened levels correlate with the Psoriasis Area and Severity Index (PASI) values, suggesting IL-18 as a potential biomarker for psoriasis." (PMID 39126010, 2024).